ABCC4 (ATP binding cassette subfamily C member 4 (PEL blood group))
Diseases named in the same sentence as ABCC4 in open-access papers (continued):
Sharing a sentence is not in itself a finding about the gene and the disease.
colitis (3 papers, 2020 to 2026). Inflammation of the colon. "Some of these genes have also been associated with an abnormal response to infection (C4A, ENSBTAG00000006864, and IER3), increased/decreased susceptibility to bacterial infection (C4A and ENSBTAG00000006864), or induced colitis (ABCC4 and IER3)." (PMID 32183688, 2020). "mRNA levels of Ptgs1, Ptgs2, Abcc4, and Hpgd were significantly decreased in LP macrophages from Slco2a1−/− mice with DSS-induced colitis when compared with their WT counterparts." (PMID 32184453, 2020).
endometrial cancer (3 papers, 2017 to 2021). Primary or metastatic malignant neoplasm involving the endometrium (mucous membrane that lines the endometrial cavity). "Among the ABC genes, there were mutations in all four genes involved in the efflux of steroid conjugates (i.e., ABCC1, ABCC4, ABCC11, ABCG2), in 5.7–8.3% of patients with endometrial cancer." (PMID 28674494, 2017).
Insulin resistance (3 papers, 2019 to 2025). Increased resistance towards insulin, that is, diminished effectiveness of insulin in reducing blood glucose levels. "Second, while we unexpectedly observed that ABCC4 inhibition significantly reduced liver TC levels and improved hepatic insulin resistance in HFD-fed mice, it is essential to further validate this effect in hepatocyte-specific Abcc4 knockout mice under metabolic stress." (PMID 41038958, 2025). "However, we observed that ABCC4 inhibition also significantly reduced liver TC levels and improved hepatic insulin resistance in HFD-fed mice." (PMID 41038958, 2025).
melanoma (3 papers, 2020 to 2022). A malignant, usually aggressive tumor composed of atypical, neoplastic melanocytes. "A query of human tumor transcriptomic data for 471 melanoma patients from The Cancer Genome Atlas (TCGA) dataset revealed a positive correlation of IGF1 and ABCC9, ABCG1, ABCB1, and ABCC4 with GHR expression, and ABCC1 with both GHR and IGF1R expression, supporting our observations." (PMID 35865483, 2022). "Analyzing specific genes involved in phenotypic plasticity, the TCGA dataset confirmed the direct and significant correlation between expression levels of molecules connected to EMT (ZEB1) and stemness (YAP1, ABCC4) molecules, as well as NAMPT in melanoma patients." (PMID 33419372, 2020).
primary biliary cirrhosis (3 papers, 2021 to 2023). "Increased expression of Abcc3 and Abcc4 is, thus, in agreement with the observation in earlier studies in primary biliary cirrhosis and acetaminophen-induced liver failure." (PMID 38053838, 2023).
pulmonary arterial hypertension (3 papers, 2013 to 2024). Pulmonary arterial hypertension (PAH) is a group of diseases characterized by mean pulmonary artery pressure >20 mmHg and elevated pulmonary arterial resistance leading to right heart failure. "It is important to highlight that ABCC4 possesses a pathogenic role in the progression of pulmonary arterial hypertension (PAH) in humans." (PMID 28900313, 2017).
rectal cancer (3 papers, 2014 to 2018). A primary or metastatic malignant neoplasm that affects the rectum. "Our study suggests that ABCC4 serves as a novel predictive biomarker that is responsible for the radioresistance and predicts a poor prognosis for locally advanced rectal carcinoma after neoadjuvant radiotherapy." (PMID 24454870, 2014). "We aimed to evaluate the predictive role of ATP-binding cassette subfamily C member 4 (ABCC4) in locally advanced rectal carcinoma and explore possible molecular mechanisms by which ABCC4 confers the resistance to neoadjuvant radiotherapy." (PMID 24454870, 2014).
acute coronary syndrome (2 papers, 2018 to 2026). Signs and symptoms related to acute ischemia of the myocardium secondary to coronary artery disease. "During conditions of elevated platelet activation such as an acute coronary syndrome, S1P can be released from human platelets in large quantities—a process which depends on thromboxane formation and the ATP-binding cassette transporter ABCC4 (MRP4)." (PMID 29795022, 2018).
cardiac hypertrophy (2 papers, 2015 to 2022). "Three of them (ABCC4, ABCC5, and ABCC11) are expressed in cardiac tissue but ABCC4 is the most studied and has been shown to enhance cAMP formation, contractility, and cardiac hypertrophy." (PMID 26483685, 2015). "Three of them (MRP4 aka ABCC4, MRP5 aka ABCC5, and MRP8 aka ABCC11) have the ability to actively extrude cAMP and cGMP from the cell and in cardiac myocytes, MRP4 has been shown to enhance cAMP formation, contractility, and cardiac hypertrophy." (PMID 26483685, 2015).
hyperlipidemia (2 papers, 2021 to 2025). "Third, although our work proposes ABCC4 inhibitor as a potential therapeutic target for hyperlipidemia, its synergistic effect with statins or PCSK9 inhibitors remains untested." (PMID 41038958, 2025).
idiopathic pulmonary arterial hypertension (2 papers, 2016 to 2017). A sporadic form of pulmonary arterial hypertension (PAH) characterized by elevated pulmonary arterial resistance leading to right heart failure. "Such elevated levels in ABCC4/MRP4 were observed in human coronary SMCs in vitro, in rat and mouse arteries after exposition to hypoxic conditions, as well as in patients with idiopathic pulmonary arterial hypertension." (PMID 28383515, 2017).
Kawasaki disease (2 papers, 2018 to 2021). A rare inflammatory disease characterized by an acute febrile, systemic, self-limiting, medium-vessel vasculitis primarily affecting children. "A previous family-based linkage study revealed that Kawasaki disease (KD) was associated with variations of the ATP-binding cassette subfamily C member 4 (ABCC4) gene in most European populations." (PMID 30363999, 2018). "Although this is the first study to investigate ABCC4 genetic polymorphisms in Southern Chinese children with Kawasaki disease, the limitations of this study should be understood." (PMID 30363999, 2018).
kidney stones (2 papers, 2014 to 2023). "Additional factors, such as sequence variation in other UA transporters (SLC22A12, SLC17A3, ABCC4 and ABCG2), age, sex, diet, drugs, physical activity, environment and volume status can influence the degree of UA tubular absorption and the risk of EIARF or nephrolithiasis." (PMID 24397858, 2014).
liver cancer (2 papers, 2022 to 2025). An epithelial or non-epithelial malignant neoplasm that arises from the liver. "Furthermore, compared to other ABC transporters like ABCC1 and ABCC4, ABCC5 more directly reflects HCC progression and drug resistance, making it highly valuable for precision medicine and targeted therapies in liver cancer." (PMID 40860808, 2025).
malignant neoplasm of the prostate (2 papers, 2020 to 2022). "We further confirmed our finding using publicly available data from PCa patients and discovered that the expression level of both ERRα and ABCC4 was significantly higher in the prostate tumor vs. the normal samples." (PMID 33014785, 2020).
osteosarcoma (2 papers, 2015 to 2021). A usually aggressive malignant bone-forming mesenchymal neoplasm, predominantly affecting adolescents and young adults. "As ABC transporters are downstream of Nrf2, the absence of Nrf2 enhanced the sensitivity of osteosarcoma to doxorubicin, cisplatin, and sorafenib and resulted in decreased expression of ABCC3, ABCC4, and ABCG2." (PMID 34473785, 2021).
pancreatic ductal adenocarcinoma (2 papers, 2020 to 2024). An infiltrating adenocarcinoma that arises from the epithelial cells of the pancreas. "The xenobiotic transporter ABCC4/MRP4 is highly expressed in pancreatic ductal adenocarcinoma (PDAC) and correlates with a more aggressive phenotype and metastatic propensity." (PMID 39114357, 2024).
Pseudoxanthoma elasticum (2 papers, 2020 to 2024). "Copy number variation in the human ABCC4 and ABCC6 genes is associated with susceptibility to esophageal squamous cell carcinoma and to the rare autosomal recessive disease pseudoxanthoma elasticum, respectively." (PMID 32770942, 2020).
pulmonary hypertension (2 papers, 2018 to 2024). Increased pressure within the pulmonary circulation due to lung or heart disorder. "Notably, inhibition of ABCC4 prevents and reverses pulmonary hypertension in mice and ABCA3 deficiency is related to PAH of the newborn." (PMID 29416681, 2018).
retinoblastoma (2 papers, 2018 to 2021). A malignant tumor that originates in the nuclear layer of the retina. "ABCC4 is transcriptional regulated by FoxM1, promoting carboplatin resistance in retinoblastoma." (PMID 34094932, 2021).
agranulocytosis (1 paper, 2024). "Reduced ABCC4 function can result in higher intracellular concentrations of toxic metabolites, contributing to cellular toxicity in the bone marrow and ultimately leading to agranulocytosis." (PMID 39508043, 2024). "This case suggests that genetic variants in renal transporters ABCG2 (exonic non-synonymous variant, rs2231137), SLC29A1 (rs747199 and rs628031), and ABCC4 (3′UTR SNP, rs3742106 and rs11568658) may contribute to drug-induced agranulocytosis." (PMID 39508043, 2024).
biliary atresia (1 paper, 2020). A rare, biliary tract disease characterized by progressive obliterative cholangiopathy of the intra- and extrahepatic bile ducts, occurring in the embryonic/ perinatal period, leading to severe and persistent neonatal jaundice and acholic stool. "Notably, ABCG2 and ABCC4 are almost absent in controls but abundant in biliary atresia; ABCB1 and ABCB4 are both significantly upregulated to the point that ABCB4 is the most abundant transporter in BA Livers, overtaking ABCD3." (PMID 33128234, 2020).
colon adenocarcinoma (1 paper, 2020). "ABCC4 was shown to modulate the compartmentalization of cAMP signaling in a colon adenocarcinoma cell line (HT29, T84), and ABCC4 inhibition with MK571 compound leads to the accumulation of cAMP at or near the plasma membrane." (PMID 33261018, 2020). "Similarly, ABCC4 was shown to modulate the compartmentalization of cAMP signaling in a colon adenocarcinoma cell lines (HT29 and T84), and ABCC4 inhibition with MK571 leads to the accumulation of cAMP at or near the plasma membrane." (PMID 33261018, 2020).
cystic fibrosis (1 paper, 2021). Autosomal recessive disorder caused by pathogenic variants in the CFTR gene (cystic fibrosis transmembrane conductance regulator), which encodes a chloride and bicarbonate channel expressed in epithelial cells, and follow the diagnosis criteria. "Subsequently, we sequenced the entire ABCC4 gene and its close relative, the cystic fibrosis associated CFTR gene, a strong AP candidate gene, in 48 cases and 47 controls." (PMID 34768335, 2021).
Ewing sarcoma (1 paper, 2018). A small round cell tumor that lacks morphologic, immunohistochemical, and electron microscopic evidence of neuroectodermal differentiation. "Interestingly, in a panel of 6 Ewing sarcoma cell lines, high basal expression levels of ABCC4 were associated with enhanced sensitivity to SP-2509 (R2 = 0.4321) with the converse for ABCB1, high basal expression was associated with decreased sensitivity (R2 = 0.4249)." (PMID 30559927, 2018).
Fanconi anemia (1 paper, 2022). Fanconi anemia (FA) is a hereditary DNA repair disorder characterized by progressive pancytopenia with bone marrow failure, variable congenital malformations and predisposition to develop hematological or solid tumors. "Besides ABCC4, POLE3, POLE4, and the Fanconi anemia pathway genes FANCF and C17orf70 are top candidates that sensitize both wild-type and TDP1-KO cells to CPT treatment." (PMID 35869071, 2022).
fibrosis (1 paper, 2021). the formation of excess fibrous connective tissue in an organ or tissue in a reparative or reactive process. "Notably, some C15 genes were previously implicated in PH supporting the accuracy of our predictions; for example, inhibition of ABCC4 improved PH in mice and identification of LGALS3 (galectin-3) as a pathogenic factor in PH and right ventricular fibrosis." (PMID 34669463, 2021).
Hypercholesterolemia (1 paper, 2025). An increased concentration of cholesterol in the blood. "Targeting ABCC4, therefore, could be a promising therapeutic strategy for hypercholesterolemia and lipid-associated metabolic disorders." (PMID 41038958, 2025).
male infertility (1 paper, 2025). The inability of the male to effect fertilization of an ovum after a specified period of unprotected intercourse. "It has been shown that mutations in the genes associated with ABC transporters, such as Abcc4 and CFTR, in the epididymis may interfere with male infertility through the malformation of the epididymis." (PMID 39997926, 2025).
myeloid leukemia (1 paper, 2017). A clonal proliferation of myeloid cells and their precursors in the bone marrow, peripheral blood, and spleen. "To determine whether endogenous ABCC4 and MPP1 directly interacted in AML cells, we performed co-immunoprecipitation experiments using MO7e cells, a myeloid leukemia cell line derived from a pediatric patient." (PMID 29146910, 2017).
NK/T-cell lymphoma (1 paper, 2018). "Here, we aimed to explore the biological roles and potential mechanism of IL-13 and ABCC4 in multidrug resistance of NK/T-cell lymphoma." (PMID 30643796, 2018). "ELISA analysis was used to determine the level of serum IL-13 and immunohistochemical analysis was applied to detect the ABCC4 expression level in patients with human NK/T-cell lymphoma." (PMID 30643796, 2018). "Levels of serum IL-13 and ABCC4 expression were observed to be upregulated in patients with human NK/T-cell lymphoma." (PMID 30643796, 2018).
oral-cancer (1 paper, 2015). "Differentially expressed microRNAs have been found to tightly regulate four of the possible biomarkers that we identified—HMGA2, EGFR, HOXA1, and ABCC5/ABCC4 —further supporting their involvement in oral-cancer progression." (PMID 26179909, 2015).
ovarian tumor (1 paper, 2025). "VOPP1 reduced PTX resistance in ovarian tumor cells by regulation of ABCC4." (PMID 40949794, 2025).
polydactyly (1 paper, 2020). A disease characterized by the presence of polydactyly, including syndromic and non-syndromic forms. "Based on the important role of cilia in SHH single transduction and the function of ABCC4 in cell ciliogenesis, we firmly suggest ABCC4 as a new candidate gene for polydactyly in pigs." (PMID 32228435, 2020). "In this research, we utilized pig as animal model in studying polydactyly and identified ABCC4 as a new candidate gene for PPD abnormal possibly through the regulation of ciliogenesis." (PMID 32228435, 2020).
postherpetic neuralgia (1 paper, 2023). "One intronic SNP in the ABCC4 gene showed a genome-wide significant association with postherpetic neuralgia using an additive model." (PMID 37144689, 2023).
pyometra (1 paper, 2021). "Further validation studies are needed to establish the direct functional consequence of the ABCC4 risk variant on the transport of prostaglandins and development of pyometra." (PMID 34404837, 2021).
rectal adenocarcinoma (1 paper, 2014).
serous ovarian cancer (1 paper, 2018). "The second identified co-expression network in serous ovarian cancer exists between ABC-transporters (ABCB2, ABCB3, and ABCC4) and HER-2." (PMID 30131693, 2018).
skin aging (1 paper, 2023). The gradual irreversible changes in structure of skin that occur as a result of the passage of time.. "Then, we confirmed the down-regulated expressions of ABCC4, PTGER3, BCEH, HPGD, and MOXD1 in normal group, while AR, CXCR2, HSD17B2, ODC1, PI3, PLAU and THBS2 were up-regulated in skin aging group." (PMID 37310405, 2023).
systemic lupus erythematosus (1 paper, 2025). An autoimmune multi-organ disease typically associated with vasculopathy and autoantibody production. "According to GSEA, ABCC4 significantly enriched 38 pathways, including cell cycle, RNA degradation, and systemic lupus erythematosus." (PMID 40475761, 2025).